YTHDF1 (YTH N6-methyladenosine RNA binding protein F1)
Diseases named in the same sentence as YTHDF1 in open-access papers (continued):
Sharing a sentence is not in itself a finding about the gene and the disease.
lung adenocarcinoma (continued). "Moreover, the expression of YTHDF1 and FTH were positively relevant in lung tissues, which indicated the clinical significance of YTHDF1-mediated m6A modification of FTH in lung adenocarcinoma occurrence and metastasis." (PMID 37259333, 2023). "Recent studies have shown that YTHDF1 and YTHDF2 are highly expressed in lung adenocarcinoma and related to the prognosis of patients, but the specific mechanism remains unclear." (PMID 33692959, 2021). "Besides, ZC3H13, ALKBH5, YTHDF1, and YTHDF2 were also positively related with each other in lung adenocarcinoma." (PMID 32398949, 2020). "In addition, another study in lung adenocarcinoma (LUAD) demonstrated that METTL3 enhances RNA stability and promotes translation of SLC7A11 through m6A-mediated binding of YTHDF1 and YTHDC2, YTHDC2 prefers to bind to m6A-modified SLC7A11 mRNA and promoting its decay." (PMID 39799112, 2025). "We have previous results showed that YTHDF1 promotes NSCLC cell proliferation and xenograft tumor formation by mediating the translational efficiency of cyclin D1, cyclin-dependent kinase 2 (CDK2), and CDK4, and that YTHDF1 elimination inhibits de novo lung adenocarcinoma (ADC) progression." (PMID 36650570, 2023). "The METTL3, YTHDF1 and YTHDF2 may be new biomarkers for the prognosis of lung adenocarcinoma." (PMID 34489709, 2021). "Interestingly, although somatic mutation is rare in EGFR/KRAS/ALK-negative lung adenocarcinoma of never-smokers, the PCDHB14 (cell adhesion) Y670S mutation and YTHDF1 (RNA binding) I492V mutations were each found in two cases (12.5%)." (PMID 24576404, 2014).
prostate carcinoma (23 papers, 2020 to 2025). A carcinoma that arises from epithelial cells of the prostate gland. "To investigate the potential therapeutic implications of YTHDF1, we subsequently aimed to examine its functional role and elucidate the underlying mechanisms through which YTHDF1 facilitates the progression of prostate cancer." (PMID 40251202, 2025). "Next, we investigated the cause of YTHDF1 dysregulation in prostate cancer." (PMID 36439881, 2022). "Moreover, our results indicated that YTHDF1 was upregulated in prostate cancer tissue and that high YTHDF1 expression was associated with adverse prognosis in patients with prostate cancer." (PMID 36439881, 2022). "By a comprehensive analysis using the TCGA (The Cancer Genome Atlas) database, we observed that YTHDF1 is highly expressed across various tumor types, including prostate cancer." (PMID 40251202, 2025). "Given that YTHDF1 facilitates the proliferation of prostate cancer cells, we uncovered that silencing YTHDF1 effectively disrupted the cell cycle transition by BrdU incorporation assay." (PMID 40251202, 2025). "In line with previous finding that RNF7 knockdown sensitizes tumor cell response to radiotherapy by increasing cellular apoptosis, we corroborated that YTHDF1 or RNF7 knockdown increased DDP-induced cellular apoptosis in prostate cancer cells." (PMID 40251202, 2025). "The ROC specificity of YTHDF1 in prostate cancer is close to 0.8, indicating its potential as an independent prognostic factor for patients with PCa." (PMID 40251202, 2025). "In conclusion, our findings emphasize the critical role of YTHDF1 in the progression of prostate cancer and suggest its potential as a therapeutic target for future clinical interventions." (PMID 40251202, 2025). "As expected, we overexpressed RNF7 in prostate cancer cell lines in combination with YTHDF1 knockdown, which counteracted the inhibitory effect of YTHDF1 knockdown on tumor cell proliferation." (PMID 40251202, 2025). "Our findings demonstrated significant overexpression of YTHDF1 in prostate cancer cell lines PC3, DU145, 22RV-1, and LNCaP, relative to the normal prostate cells RWPE-1." (PMID 40251202, 2025). "YTHDF1 in prostate cancer was also found to repress the T cell-mediated antitumor immunity and ferroptosis." (PMID 40591025, 2025). "Consistent with former findings, we unveiled that abnormal amplification of the YTHDF1 copy number leads to its overexpression in prostate cancer." (PMID 40251202, 2025). "YTHDF1 can also promote prostate cancer progression by regulating TRIM44 m6A modification and degradation." (PMID 40830264, 2025). "The receiver operating characteristic (ROC) curve analysis demonstrated an AUC value of 0.749 for YTHDF1, suggesting its potential as an independent biomarker for prostate cancer." (PMID 40251202, 2025). "Concurrently, our tissue microarray analysis revealed that YTHDF1 was significantly overexpressed in prostate cancer tissues." (PMID 40251202, 2025). "yTHDF1 can also contribute to prostate cancer progression by regulating TRIM44 to promote PCa cell proliferation and migration." (PMID 38166703, 2024). "YTHDF1 was highly expressed in both prostate cancer (PCa) tissues and cells, and the high level of YTHDF1 was also associated with relatively poor prognosis of PCa patients." (PMID 36707507, 2023). "Patients with higher YTHDF1 expression show a worse prognosis whereas YTHDF1 knockdown significantly inhibits prostate cancer cells proliferation, migration, and invasion via modulating the expression of TRIM44." (PMID 36650570, 2023). "YTHDF1-overexpression promoted cell proliferation and colony-forming ability of prostate cancer cells." (PMID 36439881, 2022).
prostate carcinoma (continued). "We obtained a comprehensive view of YTHDF1-mediated translation and gene regulation in prostate cancer by integrating RNA-seq, RIP-seq, m6A-seq, and TMT proteomic analyses." (PMID 36439881, 2022). "Our study identified PLK1, a key factor in the cell cycle, as the direct target of YTHDF1 in prostate cancer cells." (PMID 36439881, 2022). "In this study we showed the upregulation of YTHDF1 in prostate cancer and its role in regulating prostate cancer tumorigenesis and metastasis through the induction of PLK1 mRNA translational efficiency in an m6A modification-dependent manner." (PMID 36439881, 2022). "In the current study, we aimed to elucidate the role of YTH m6A RNA-binding protein 1 (YTHDF1), a “reader” of m6A modification, in prostate cancer tumorigenesis." (PMID 36439881, 2022). "Our data demonstrated that overexpression of ELK1 in prostate cancer cells contributed to the transcriptional activation of YTHDF1, further resulting in aberrant regulation of PLK1/PI3K/AKT axis." (PMID 36439881, 2022). "In summary, these data demonstrated that YTHDF1-overexpression promoted the tumorigenesis and metastasis of prostate cancer." (PMID 36439881, 2022). "Consistent with previous studies, when YTHDF1 was knocked out in prostate cancer cells, the RNA level of PLK1 was relatively unchanged, whereas a prominent decrease in the protein level was observed." (PMID 36439881, 2022). "Consistently, prostate cancer tissues had significantly higher YTHDF1 mRNA expression than normal tissues according to The Cancer Genome Atlas (TCGA) database." (PMID 36439881, 2022). "To sum up, we demonstrated that YTHDF1 promoted prostate cancer progression by increasing the translational efficiency of PLK1 in an m6A dependent manner." (PMID 36439881, 2022). "To investigate the oncogenic role of YTHDF1 in prostate cancer, we established stable YTHDF1-knockdown PC-3 and DU145 cell lines." (PMID 36439881, 2022). "To further evaluate the role of YTHDF1 in prostate cancer in vivo, we performed in vivo orthotopic implantation experiments where the cells were injected subcutaneously into the flanks of BALB/c nude mice." (PMID 36439881, 2022). "Knocking out YTHDF1 inhibited proliferation, migration, and invasion of prostate cancer cells in vitro and in vivo." (PMID 36439881, 2022). "To further elucidate the oncogenic role of YTHDF1/PLK1 axis prostate cancer cells, we overexpressed PLK1 in YTHDF1-deficient PC-3 and DU145 cells." (PMID 36439881, 2022). "Next, we evaluated the impact of YTHDF1-KO on prostate cancer metastatic colonization using tail vein injection assay." (PMID 36439881, 2022). "Mechanistically, we identified the target genes of YTHDF1 which are involved in prostate cancer progression." (PMID 36439881, 2022). "Moreover, RNA-binding motif protein 15B (RBM15B) enhances prostate cancer cell proliferation by increasing the stability of proliferating cell nuclear antigen (PCNA) mRNA through YTHDF1-induced m6A methylation." (PMID 40986143, 2025). "To explore the clinical application of YTHDF1 in prostate cancer, we decided to examine whether inhibiting YTHDF1 would be able to increase tumor cell sensitivity to chemotherapy drug." (PMID 40251202, 2025). "Therefore, we assessed the ubiquitination status of p27 in prostate cancer cells and observed a significant reduction in its ubiquitination level following YTHDF1 knockdown." (PMID 40251202, 2025). "To validate the critical role of YTHDF1/RNF7/p27 in prostate cancer, we initially assessed RNF7 expression in a prostate cancer tissue microarray and observed a positive correlation between RNF7 and YTHDF1 proteins, without detecting significant change in RNF7 mRNAs." (PMID 40251202, 2025). "Therefore, elucidating the functional dynamics and downstream targets of YTHDF1 in prostate cancer is imperative for advancing clinical precision oncology." (PMID 40251202, 2025). "This study revealed that YTHDF1 overexpressed in prostate cancer cells and tissues." (PMID 40251202, 2025).
prostate carcinoma (continued). "YTHDF1 is overexpressed in prostate cancer tissues and cells." (PMID 36650570, 2023). "YTHDF1 was upregulated in prostate cancer tissue, and high YTHDF1 expression could predict the poor prognosis of patients with prostate cancer." (PMID 36835633, 2023). "In prostate cancer, the overexpression of YTHDF1 often inhibits tumor ferroptosis." (PMID 38202722, 2023). "In addition, RT-qPCR and western blotting analyses also confirmed the higher expression of YTHDF1 in prostate cancer cell lines (PC-3 and DU145) than in the normal prostate epithelial cell line (RWPE-1)." (PMID 36439881, 2022). "In addition, ChIP-qPCR assays suggested that ELK1 directly bound to the binding site 1 and 2 of YTHDF1 promoter region in prostate cancer cells." (PMID 36439881, 2022). "Furthermore, upregulation of YTHDF1 promoted prostate cancer tumorigenesis and metastasis in vitro and in vivo." (PMID 36439881, 2022). "In summary, YTHDF1-KO impaired the tumorigenesis and metastasis of prostate cancer." (PMID 36439881, 2022). "Moreover, YTHDF1 regulated prostate cancer growth and metastasis via increasing translational efficiency of polo-like kinase 1 (PLK1) in an m6A dependent manner, and the transcription of YTHDF1 was activated by the dysregulation of ELK1 in prostate cancer." (PMID 36439881, 2022). "To elucidate the underlying mechanisms of YTHDF1 in prostate cancer progression, we performed RNA profiling of YTHDF1-KO and negative control PC-3 cells." (PMID 36439881, 2022). "Here, we identified YTHDF1 as a poor prognostic indicator for prostate cancer progression." (PMID 36439881, 2022). "Thus, our results demonstrated that YTHDF1 transcription was activated by aberrant ELK1 in prostate cancer." (PMID 36439881, 2022). "Thus, our results demonstrated the prominent oncogenic role of the m6A reader YTHDF1 in prostate cancer development." (PMID 36439881, 2022). "In addition, overexpression of YTHDF1 facilitated prostate cancer proliferation, migration, and invasion in vitro and in vivo." (PMID 36439881, 2022). "Here, we report significant upregulation of YTHDF1 in prostate cancer tissues." (PMID 36439881, 2022). "Consistent with previous studies, we found that YTHDF1 was highly expressed in prostate cancer cells and reduced expression of YTHDF1 inhibited PCa cell proliferation, migration, and invasion, suggesting that YTHDF1 may represent a target for PCa treatment." (PMID 34677810, 2021). "The findings suggest that YTHDF1 may play a role in prostate cancer pathogenesis." (PMID 40251202, 2025). "Furthermore, YTHDF1 correlates with the stages of prostate cancer, while it did not exhibit a significant association with prostate cancer metastasis." (PMID 40251202, 2025). "Finally, we demonstrated that ELK1 contributed to YTHDF1 overexpression in prostate cancer." (PMID 36439881, 2022). "To test directly whether YTHDF1-overexpression could have an effect on the metastatic capacity of prostate cancer, we performed an experimental model of metastasis where lung colonization of prostate cancer cells following tail vein injection was assessed." (PMID 36439881, 2022). "Our findings are consistent with previous studies, we showed that knockdown of YTHDF1 inhibits RNF7 expression, resulting in abnormal ROS accumulation upon DDP treatment in prostate cancer, while overexpression of RNF7 can reverse this effect." (PMID 40251202, 2025). "The demethylase ALKBH5 with m6A binding proteins YTHDF1/2/3, concurrently, played a suppression role in the regulation of NSCLC tumor growth and metastasis, while FTO inhibits tumorigenesis in prostate cancer." (PMID 41157107, 2025). "We assessed the clinical potential of YTHDF1 in prostate cancer treatment by evaluating the therapeutic efficacy of the neddylation inhibitor MLN4924 using both in vitro and in vivo prostate cancer models." (PMID 40251202, 2025).
prostate carcinoma (continued). "For example, through the m6A-PD-L1 axis, the m6A reader YTHDF1 has been shown to reduce ferroptosis and impair CD8+ T cell-mediated anti-tumor immunity in prostate cancer (PCa)." (PMID 40271153, 2025). "At the same time, YTHDF1 can also repress the CD8+ T cell-mediated anti-cancer immunity and ferroptosis in prostate cancer in an m6A/PD-L1 manner." (PMID 40830264, 2025). "ELK1-activated YTHDF1 controls PLK1 translation efficiency in an m6A-dependent manner, enabling the activation of the PI3K/AKT signaling pathway, leading to prostate cancer progression." (PMID 38166703, 2024). "However, the oncogenic role of YTHDF1 in prostate cancer remains unclear." (PMID 36439881, 2022). "Seven m6A methylation-related genes (ALKBH5, FMR1, IGFBP3, RBM15B, YTHDF1, YTHDF2, and ZC3H13) were identified as cross-talk genes between prostate cancer and PD." (PMID 36133437, 2022). "Consistent with the knockdown of YTHDF1 in PC-3 and DU145 cells, knockout of YTHDF1 significantly impaired cell proliferation and colony-forming ability in prostate cancer cells." (PMID 36439881, 2022). "To further elucidate the role of YTHDF1 in prostate cancer, we established stable YTHDF1-overexpression PC-3 and DU145 cells and confirmed the YTHDF1 overexpression at the protein level." (PMID 36439881, 2022). "Therefore, targeting YTHDF1 may be a promising therapeutic strategy for prostate cancer therapy." (PMID 36439881, 2022). "Some researchers analyzed the important m6A RNA regulators, which act as prognosis factors in prostate cancer, and identified RBMX, NXF1, YTHDF1, HNRNPA2B1, and TRMT112 as critical genes that have great effects on the prognosis of PCa patients." (PMID 34899855, 2021). "The expression of YTHDF1/2 is elevated in bladder cancer, and the expression of YTHDF2 is elevated in prostate cancer." (PMID 32808488, 2020). "Given the observed alteration in the proteins of cyclin p27, we did not observe that YTHDF1 bound to p27 mRNA, indicating that YTHDF1 promotes tumor cell proliferation via a novel target in prostate cancer." (PMID 40251202, 2025). "Previous literature indicated that YTHDF1 could mediate the m6A modification on TRIM68 to accelerate cellular viability, migration and invasion of prostate cancer." (PMID 39557826, 2024). "In addition, the expression levels of METTL3, FTO (Zhu, Li & Xu, 2021), YTHDF1-2, YTHDC2 were positively correlated with the Gleason score of prostate cancer." (PMID 37701836, 2023). "In prostate cancer, m6A modification level was upregulated, and the expression levels of METTL3, METTL14, VIRMA, RNA binding motif protein 15 (RBM15), HNRNPC, HNRNPA2B1, YTHDC2, YTHDF1 and YTHDF2 increased." (PMID 37701836, 2023). "In our studies, we suggested that m6A modification of PLK1 mRNA could be recognized by m6A “reader” YTHDF1, which then induced PLK1 translational rate in prostate cancer, thus promoting prostate cancer progression." (PMID 36439881, 2022). "YTHDF1 and YTHDF2 play critical roles in both bladder cancer and prostate cancer." (PMID 32808488, 2020). "Therefore, we hypothesized that YTHDF1 could affect PI3K/AKT pathway activation by regulating the protein level of PLK1, thereby promoting prostate cancer tumorigenesis and metastasis." (PMID 36439881, 2022). "The results indicated that YTHDF1 does not bind to the mRNAs of CDK2 and CDK4 in prostate cancer cells." (PMID 40251202, 2025). "However, the expression patterns of the other four genes (ALKBH5, RBM15B, YTHDF1, and YTHDF2) in prostate cancer and periodontitis were not consistent." (PMID 36133437, 2022).